MIR6855 (microRNA 6855)
Synonyms: hsa-mir-6855
Gene: MicroRNA gene on chromosome 9 (129,869,605 to 129,869,671, forward strand). Ensembl gene ENSG00000276124.
Homologues: Orthologues: chimpanzee MIR6855 (100% identical).